COMP (cartilage oligomeric matrix protein)
Diseases named in the same sentence as COMP in open-access papers (continued):
Sharing a sentence is not in itself a finding about the gene and the disease.
colon carcinoma (continued). "Despite the fact that an integrative analysis based on independent datasets was undertaken and certain findings with potential values for therapeutic application were achieved, the role of COMP in the prognosis and immunotherapy for colon cancer should be prospectively validated." (PMID 36671447, 2022). "The COMP gene predictor increases colon cancer cell proliferation and may be a predictor in BC." (PMID 36895470, 2023). "Our findings showed that COMP was highly associated with CAF abundance and stromal score, which was followed by the validation of COMP coexpression with ACTA2 in clinical samples, indicating that COMP expression may partially reflect CAF abundance in colon cancer." (PMID 36671447, 2022). "Hence, COMP could act as a novel therapeutic target as well as a promising predictor for immune therapeutic response and prognosis in colon cancer." (PMID 36671447, 2022). "By knocking out COMP with CRISPR technology, the proliferation ability of colon cancer cells was weakened." (PMID 37020597, 2023). "All these results indicate that COMP-induced M2 macrophage infiltration impaired the high activity of antitumor immune processes, and the treatment targeting COMP may reverse the M2 immunosuppression phenotype and be instrumental for immunotherapy in colon cancer patients." (PMID 36671447, 2022). "Moreover, the coexpression of COMP, ACTA2, and CD206 was found in colon cancer specimens, especially in the high-COMP expression subgroup." (PMID 36671447, 2022). "Thus, the COMP-related mitochondrial electron transport process might participate in TGF-β-induced redox imbalance, which may partly explain the higher rates of pulmonary metastasis in rectal cancer patients than colon cancer patients." (PMID 36551305, 2022).
prostate carcinoma (23 papers, 2011 to 2026). A carcinoma that arises from epithelial cells of the prostate gland. "We identified a novel gene risk panel comprising six genes (SSTR1, CA14, HJURP, KRTAP5-1, VGF, and COMP) for prostate cancer risk classification." (PMID 40592939, 2025). "COMP overexpression in tumor cells was highly associated with poorer OS and recurrence-free survival of breast and prostate cancer patients." (PMID 38615020, 2024). "A high COMP level was related to a high risk for prostate cancer patients with a higher fraction of regulatory T cells and M2 macrophages." (PMID 36551305, 2022). "In this study, we aimed to further characterize the molecular mechanism underlying the pathophysiological role of COMP in prostate cancer." (PMID 29228690, 2017). "In prostate cancer cells, COMP is associated with cancer recurrence." (PMID 36114508, 2022). "Proliferation and invasion were marginally greater in the non-irradiated cells with COMP overexpression, similar to previous studies that identified COMP expression in breast and prostate cancer promotes invasion and growth." (PMID 40141111, 2025). "A similar result was also observed in prostate cancer cells exposed to staurosporine and treated with recombinant COMP." (PMID 38615020, 2024). "COMP has been shown to promote the progression of breast, colon, and prostate cancers in recent studies." (PMID 39867879, 2024). "We also demonstrated that reducing endoplasmic reticulum (ER) stress resulted in the down-regulation of apoptosis in cancer cells expressing COMP, and this was achieved by preventing Ca2+ release from the ER of prostate cancer cells." (PMID 38965233, 2024). "We previously reported that COMP confers resistance to apoptosis in prostate cancer cells, but the molecular mechanism responsible for this phenomenon has not been studied in depth." (PMID 38965233, 2024). "For example, COMP correlates with TIME in prostate cancer and bladder cancer and can be a prognostic biomarkers." (PMID 36910014, 2023). "MT1G, MSMB, SLC22A3, COMP and KRT15 have also been associated with aggressive and/or poor clinical outcome in prostate cancer." (PMID 36661662, 2022). "Research has shown that COMP is overexpressed in colon, breast, and prostate cancers and is closely related to tumorigenesis 18-20." (PMID 33613749, 2021). "We showed previously that COMP is expressed in prostate cancer where it is correlated with a poorer survival of patients." (PMID 31737569, 2019). "In a previous study we showed that prostate cancer cells that express COMP in vitro were resistant in Docetaxel induced apoptosis." (PMID 31737569, 2019). "Datasets deposited into the Oncomine database further support an upregulation of COMP expression in prostate cancer as compared to healthy tissue." (PMID 29228690, 2017). "Since it has previously been shown that COMP can both act as an inhibitor and activator of the complement system, we investigated how complement attack on prostate cancer cells expressing COMP was affected." (PMID 29228690, 2017). "COMP expression enhanced the invasion of prostate cancer cells in vitro, and this effect was lost after inhibition of Src- or integrin-signalling." (PMID 29228690, 2017). "Taken together, these data show that prostate cancer cells expressing COMP had impaired intracellular Ca2+ signalling, which led to altered cellular metabolism and enhanced protection against apoptosis." (PMID 29228690, 2017). "After inducing ER stress with Brefeldin A in DU145 cells, we found that COMP had a similar protective role in prostate cancer cells, as its expression increased the number of live cells and decreased the proportion of apoptotic (annexin V positive) cells." (PMID 29228690, 2017). "Taken together, these data showed that COMP protected prostate cancer cells against several different types of apoptosis." (PMID 29228690, 2017).
prostate carcinoma (continued). "In conclusion, this study shows that COMP expression in prostate cancer correlated with enhanced invasion and with a more progressive disease." (PMID 29228690, 2017). "In conclusion, COMP is a potent driver of the progression of prostate cancer, acting in an anti-apoptotic fashion by interfering with the Ca2+ homeostasis of cancer cells." (PMID 29228690, 2017). "The expression of COMP in prostate cancer cells correlated with a more aggressive disease with faster recurrence." (PMID 29228690, 2017). "Increase in COMP and periostin expression and decrease in VAP-1 expression in prostate have been shown to be associated with aggressive prostate cancer." (PMID 26023718, 2015). "Moreover, when prostate cancer cells expressing COMP were treated with TNF-α, they exhibited protection against apoptosis." (PMID 38965233, 2024). "Also, prostate cancer cells which present an increased expression level of COMP are protected against apoptosis and have an enhanced Warburg effect." (PMID 36114508, 2022). "Moreover, we showed that COMP expressing prostate cancer cells develop resistance to apoptosis triggered by different compounds with exception of those that target the nuclear topoisomerase." (PMID 31737569, 2019). "Recent translational research described a novel pathway that stimulated prostate cancer progression in vivo and in vitro including Cartilage Oligomeric Matrix Protein (COMP); a small (54 kD) molecule most commonly found in the extracellular matrix (ECM) of cartilage." (PMID 31413818, 2019). "Thus, prostate cancer cells expressing COMP showed a reduced oxygen consumption rate in response to glucose, as well as during uncoupling, reflecting the maximal respiratory rate." (PMID 29228690, 2017). "The increased invasiveness could be neutralized with Cilengitide, suggesting that surface-bound COMP mediates invasion of prostate cancer cells via its interaction with integrins." (PMID 29228690, 2017). "In support of such a hypothesis, we showed that COMP bound to the surface of prostate cancer cells." (PMID 29228690, 2017). "Thus, we hypothesize that either the presence of COMP affects a fundamental cellular process, such as the previously demonstrated inhibition of calcium release from the ER in the context of prostate cancer, or multiple anti-apoptotic cellular mechanisms are impacted." (PMID 38965233, 2024). "However, one may hypothesize that the worse prognosis of serum COMP positive patients under the treatment of taxanes is due to COMP-mediated apoptotic resistance by a similar calcium metabolism related mechanism as described in prostate cancer." (PMID 31737569, 2019). "COMP did not significantly affect ovarian cancer cell proliferation in vitro, as also observed with breast and prostate cancer cells, consistent with no observed correlation between COMP in cancer cells and Ki67 by immunochemistry analysis." (PMID 38615020, 2024). "COMP expression can also protect DU145 cells against apoptosis induced by Docetaxel, which is a tubulin-disrupting chemotherapy drug currently used in the treatment of prostate cancer." (PMID 29228690, 2017).
hepatocellular carcinoma (20 papers, 2018 to 2025). A malignant tumor that arises from hepatocytes. "Cartilage oligomeric matrix protein (COMP) is an extracellular matrix protein that has recently been associated with worse patient outcomes in breast, prostate, colorectal and hepatocellular cancers." (PMID 40141111, 2025). "Growing evidence has unveiled associations of COMP expression with a worse outcome in several solid cancer types, including breast, prostate, colorectal, bladder, and hepatocellular carcinoma." (PMID 38615020, 2024). "Elevated serum COMP is strongly associated with hepatocellular carcinoma (HCC) progression, suggesting that it can be used for non-invasive assessments of HCC progression." (PMID 36012514, 2022). "Further, the phosphorylation of ERK and AKT in COMP-treated hepatocellular carcinoma cells resulted in the activation of MEK/ERK and PI3K/AKT pathways and eventually induced the migration ability of cells." (PMID 38615020, 2024). "Our previous study reveals that hepatic stellate cells (HSCs)-derived cartilage oligomeric matrix protein (COMP) contributes to hepatocellular carcinoma (HCC) progression." (PMID 30999932, 2019). "Association between clinicopathological parameters and serum COMP level in primary hepatocellular carcinoma." (PMID 30231922, 2018). "Moreover, hepatocellular carcinoma (HCC) cells treated with recombinant COMP enhanced migration and invasion which was found to be related with the PI3k/AKT pathway through the CD36 receptor, a known receptor for the thrombospondin family." (PMID 40141111, 2025). "And CAFs can drive FN1, COMP to regulate tumor metastasis and stemness in hepatocellular carcinoma." (PMID 38549156, 2024). "Thus, the data suggest that COMP plays an important role in the dynamic interactions between cancer cells and activated HSCs in the progression of hepatocellular carcinoma." (PMID 30231922, 2018). "Moreover, COMP could promote progression of hepatocellular carcinoma by activating the MEK/ERK and PI3K/AKT signaling pathways." (PMID 38584705, 2024). "In hepatocellular carcinoma, MEK and PI3K inhibitors abrogated the COMP-induced EMT, which was related to COMP interaction with CD36 receptors." (PMID 38615020, 2024). "RvD1 inhibits the secretion of a cartilage oligomeric matrix protein (COMP) by targeting FPR1/ROS/ROXM1 signaling, thereby impeding the cancer stem-like properties and EMT of hepatocellular carcinoma cells." (PMID 36499209, 2022). "The cartilage oligomeric matrix protein (COMP) and Golgi-protein-73 (GP73) have been proposed as markers of liver fibrosis and hepatocellular carcinoma (HCC)." (PMID 34298722, 2021).
knee osteoarthritis (18 papers, 2006 to 2026). "For example, an eDMC (cg02961385) was localized near a gene, COMP, which was shown to be a novel diagnostic and prognostic biomarker for knee osteoarthritis." (PMID 31900157, 2020). "Moreover, the levels of COMP increase with the severity of the disease and thus it is regarded as a diagnostic and prognostic biomarker in knee osteoarthritis." (PMID 30105061, 2018). "Specific serum biomarkers of cartilage metabolism such as cartilage oligomeric matrix protein (sCOMP) and procollagen type II C-terminal propeptide (sPIICP) as well as hyaluronan (sHA), a biomarker of synovitis, have been implicated in the pathophysiology of knee osteoarthritis (OA)." (PMID 35236298, 2022). "Overall, the results highlight that serum COMP serves as a more reliable biomarker for reflecting cartilage degeneration severity in knee osteoarthritis compared to 25(OH)D levels." (PMID 41515614, 2026). "Partan & Putra (2024) discovered a significant and strong negative correlation between 25-hydroxyvitamin D [25(OH)D] and COMP serum in knee osteoarthritis." (PMID 41515614, 2026). "It is well known that COMP, a prominent constituent of articular cartilage, has been reported to increase in patients with knee osteoarthritis (OA) and early RA." (PMID 36362183, 2022). "Increased level of COMP protein is also found in knee osteoarthritis cases in comparison with healthy control." (PMID 31665048, 2019). "Elevated levels of serum TNF-α are observed in patients with knee osteoarthritis, which, similar to COMP, also increase with the severity of disease." (PMID 30105061, 2018). "The measurement of cartilage oligomeric matrix protein (COMP) has become a novel way for the diagnosis of knee osteoarthritis (OA)." (PMID 30340615, 2018). "The correct title is: Correlation of serum cartilage oligomeric matrix protein (COMP) and interleukin-16 (IL-16) levels with disease severity in primary knee osteoarthritis: A pilot study in a Malaysian population." (PMID 29281738, 2017). "In a recent study, COMP was used as a biomarker for knee osteoarthritis." (PMID 30188931, 2018). "Recent studies showed that serum levels of COMP are elevated in patients with knee osteoarthritis." (PMID 30105061, 2018). "Therefore, serum COMP measurement may be considered a useful non-invasive biomarker for the early evaluation of knee osteoarthritis, facilitating timely detection and management of degenerative joint changes." (PMID 41515614, 2026). "The roles of C-reactive protein (CRP) and cartilage oligomeric matrix protein (COMP) in knee osteoarthritis (KOA) remain controversial, thus the present study is aimed to explore the relationships between CRP, COMP, and the incidence/progression of KOA." (PMID 29351749, 2018). "The aim of this study was to investigate the correlations between serum cartilage oligomeric matrix protein (COMP), interleukin-16 (IL-16) and different grades of knee osteoarthritis (KOA) in Malaysian subjects." (PMID 28910372, 2017). "Previously, we reported that in patients with knee osteoarthritis, PEN serum concentrations were increased compared with healthy controls, and correlated with a cartilage destruction marker (cartilage oligomeric matrix protein) in synovial fluid." (PMID 27448601, 2016). "This study demonstrated a strong and statistically significant positive correlation between serum Cartilage Oligomeric Matrix Protein (COMP) levels and the degree of articular cartilage degradation in patients with knee osteoarthritis, as assessed by both USG and MRI." (PMID 41515614, 2026). "The correct citation is: Das Gupta E, Ng WR, Wong SF, Bhurhanudeen AK, Yeap SS (2017) Correlation of serum cartilage oligomeric matrix protein (COMP) and interleukin-16 (IL-16) levels with disease severity in primary knee osteoarthritis: A pilot study in a Malaysian population." (PMID 29281738, 2017).
idiopathic pulmonary fibrosis (16 papers, 2013 to 2025). Idiopathic pulmonary fibrosis (IPF) is a nonneoplastic pulmonary disease that is characterized by the formation of scar tissue within the lungs in the absence of any known cause. "In idiopathic pulmonary fibrosis, Kaminski and colleagues reported a 13-fold increase of COMP expression in damaged lung tissue, also finding COMP serum levels were associated with pulmonary function decline as measured by forced vital capacity." (PMID 28114331, 2017). "The serum level of cartilage oligomeric matrix protein (COMP), a molecule that has been associated with skin and lung fibrosis as we describe below, also showed correlation with disease severity." (PMID 26168983, 2015). "COMP is a biomarker associated with the severity of pulmonary fibrosis in systemic sclerosis." (PMID 36507532, 2022). "COMP has been used as a biomarker for idiopathic pulmonary fibrosis and cartilage degeneration in OA and RA and traumatic joint injury." (PMID 41009743, 2025). "In clinical practice, COMP is regarded as a biomarker for idiopathic pulmonary fibrosis and cartilage degeneration, as well as a prognostic marker for joint damage in rheumatic diseases." (PMID 38577622, 2024). "Other studies also found correlation of serum KL-6, as well as COMP, with lung fibrosis." (PMID 26168983, 2015). "Biomarkers previously associated with pathobiology and/or progression in pulmonary fibrosis were selected to reflect cellular senescence (telomere length), pulmonary epithelium (SP-D, RAGE), myeloid activation (CXCL13, YKL40, CCL18, OPN) and fibroblast activation (POSTN, COMP, PROC3)." (PMID 38753183, 2024). "It indicated COMP maybe a biomarker for pulmonary fibrosis but not a causative factor in bleomycin-induced fibrosis." (PMID 36685820, 2022). "COMP regulates the TGF-β signaling pathway in skin, pulmonary fibrosis, and, in atrial fibrosis, is a major pathogenetic factor acting in combination with Ang 2 in the development of atrial fibrillation." (PMID 41009743, 2025). "COMP regulates the TGF-β signaling pathway in skin, pulmonary fibrosis and in atrial fibrosis and is a major pathogenetic factor acting in combination with Ang 2 in the development of atrial fibrillation." (PMID 41009743, 2025). "The involvement of COMP is also implied in idiopathic pulmonary fibrosis (IPF)." (PMID 36012514, 2022). "We feel that the co-localization of vimentin, pSMAD3 and COMP in fibrotic foci in human IPF lungs suggests that TGF-β1 induces COMP secretion mostly in fibrotic regions of IPF lungs and to some extent more informative than using a limited model of lung fibrosis." (PMID 24376648, 2013). "While increases in COMP have not been reported in lung fibrosis, we noticed that COMP was increased in some of our microarray datasets." (PMID 24376648, 2013). "COMP, a non-collagen ECM protein, and TNC are both upregulated in the context of pulmonary fibrosis, which JUN signaling also mediates." (PMID 32792541, 2020).